IL13 (interleukin 13)
Diseases named in the same sentence as IL13 in open-access papers (continued):
Sharing a sentence is not in itself a finding about the gene and the disease.
skin infection (4 papers, 2015 to 2025). An inflammatory process affecting the skin, caused by bacteria, viruses, parasites, or fungi. "The addition of CLA identified memory CLA+ Th17 suppression and memory CLA–IL-4+IL-13+ (Th2) expansion as additional mediators in the skin-homing response in patients with S. aureus skin infection." (PMID 38716729, 2024). "An association was confirmed between disease severity and transcription of the Th2 cytokines IL-4 and IL-13, and up-regulation of the Th17 cytokines IL-17 and IL-23 in pigs with crusted scabies." (PMID 25730203, 2015). "In addition, studies using skin infection models have demonstrated that eosinophil-derived IL-4 and IL-13 can sustain M2-like dermal resident macrophages and maintain skin barrier homeostasis, thereby limiting inflammation and promoting tissue repair." (PMID 41573250, 2025). "Levels of the proinflammatory cytokines IL-1, IL-6, and TNF-α were elevated during wound healing, consistent with previously reported results showing elevated IL-1, IL-6, IL-10, TNF-α, IL-2, IL-8, IL-13 and granulocyte colony-stimulating factor (G-CSF) in the skin infection wound model." (PMID 36901790, 2023).
toxocariasis (4 papers, 2021 to 2025). A parasitic infection caused by worms found in domestic animals. "In contrast, in toxocariasis, Th2 cells are involved; they secrete IL-4, IL-5, IL-9, IL-10, and IL-13 and promote type 2 immunity, characterized by high antibody titers." (PMID 40943043, 2025).
viral myocarditis (4 papers, 2017 to 2024). Myocarditis that is caused by an infection with a viral agent. "Recent reports have demonstrated an essential role of cytokines, like interleukin-13 (IL-13), in the pathogenesis of viral myocarditis, while the underlying mechanisms remain poorly defined." (PMID 29245918, 2017). "Indeed, we found that the total T cells were decreased by IL-13, as a direct cause for the attenuation of the viral myocarditis." (PMID 29245918, 2017). "This is consistent with a previous study showing that IL-13 induces M2 polarization, leading to improved cardiac function and reduced heart injury in a viral myocarditis mouse model." (PMID 37508517, 2023). "A previous study showed that IL-13 induces M2 polarization, leading to improved cardiac function and reduced heart injury in a viral myocarditis mouse model." (PMID 37628775, 2023). "Here, using a coxsackie virus B3 (CVB3)-infection model in BALB/C mice, we showed that IL-13 protected mouse heart function in viral myocarditis, seemingly through reduction in T lymphocyte immunity and induction of M2 macrophage polarization." (PMID 29245918, 2017). "Since T lymphocytes are key players in the development of viral myocarditis, and since IL-13 is believed to be predominantly macrophage regulator, we used flow cytometry to examine these 2 populations in the mouse heart." (PMID 29245918, 2017). "To summarize, our study contributes to a clear demonstration of an IL-13-mediated protective pathway in the pathogenesis of viral myocarditis." (PMID 29245918, 2017). "In the current study, we investigated the effects of application of IL-13 treatment on cardiac Injury and protection of heart function in viral myocarditis as well as the involvement of macrophage polarization in the process." (PMID 29245918, 2017). "Interestingly, IL-13 knockout (KO) mice was later found to develop enhanced experimental viral myocarditis in BALB/C mice." (PMID 29245918, 2017). "Together, our data suggest that application of IL-13 treatment may reduce cardiac Injury and protect heart function in viral myocarditis via enhanced M2 macrophage polarization." (PMID 29245918, 2017). "But when taking into concern of the specificity of target cells, modulation of IL-13, rather than IL-4, should have relative clearer effects on immunity, which results in the complete opposite effects of them on viral myocarditis." (PMID 29245918, 2017). "Unlike IL-4, IL-13 knockout (KO) mice develop enhanced experimental viral myocarditis in BALB/C mice, but the effects of IL-13 treatment have not been examined." (PMID 29245918, 2017).
acute kidney injury (3 papers, 2023 to 2024). Sudden and sustained deterioration of the kidney function characterized by decreased glomerular filtration rate, increased serum creatinine or oliguria. "Cytokine IL-13 plays a crucial role in the polarization of macrophages/dendritic cells to an M2 phenotype, which is essential for recovery from acute kidney injury." (PMID 38794117, 2024).
age-related macular degeneration (3 papers, 2016 to 2025). Age-related loss of vision in the central portion of the retina (macula), secondary to retinal degeneration. "However, higher IL-13 levels have been identified in the aqueous humor of patients with age-related macular degeneration." (PMID 41002723, 2025).
allergic bronchopulmonary aspergillosis (3 papers, 2018 to 2024). Allergic bronchopulmonary aspergillosis (ABPA) is a rare immunologic pulmonary disorder caused by hypersensitivity to Aspergillus fumigatus, clinically manifesting with poorly controlled asthma and recurrent pulmonary infiltrates. "In contrast, in patients with allergic bronchopulmonary aspergillosis (ABPA), A. fumigatus-specific Th2 CD4+ T cells are predominant and a recent work has identified SNPs in genes related with Th2 responses like IL13 and IL4R that increase ABPA susceptibility." (PMID 30459771, 2018). "For example, allergic bronchopulmonary aspergillosis (ABPA) is characterized by Th2 and Th9 cell-type immunity and involves interleukin (IL)-4, IL-5, IL-13, and IL-10." (PMID 38667922, 2024).
allergic pneumonitis (3 papers, 2021 to 2023). "Furthermore, pirfenidone was suggested as a viable treatment option that protected against CYP-induced steroid-resistant allergic pneumonitis via M1 macrophage polarization suppression by modulating IL-13/STAT6 and INF-γ/p38 pathways." (PMID 37048067, 2023). "In addition, IL-13 is essential for maintaining mucosal homeostasis, and overexpression of IL-13 increases airway hyperresponsiveness, exacerbates hypersensitivity pneumonitis, and limits airway tissue remodeling." (PMID 36362440, 2022). "The IL-13, MUC5AC, STAT6, and p38 mRNA expression showed a significant rise (p < 0.001) in the allergic pneumonitis group when compared to the control gene values." (PMID 37048067, 2023). "Furthermore, CYP exposure in the allergic pneumonitis rats resulted in more increase (p < 0.003) in MUC5AC and p38 gene expression (respectively); meanwhile, the IL-13 and STAT6 (respectively) showed a further decrease (p < 0.05), in comparison to the allergic pneumonitis-only group." (PMID 37048067, 2023).
aneurysm (3 papers, 2009 to 2022). Bulging or ballooning in an area of an artery secondary to arterial wall weakening. "A significant reduction in vascular IL-6 expression and reduced protein levels of IL-8, IL-13 and GM-CSF have been observed already after two weeks of doxycycline treatment (50–300 mg/day) in patients scheduled for aneurysm surgery." (PMID 22876748, 2012).
appendicitis (3 papers, 2022 to 2024). Acute inflammation of the vermiform appendix. "A recent prospective study in children showed that high levels of IL-13 appear to be associated with an increased risk of complicated appendicitis." (PMID 38673802, 2024). "In the univariate logistic regression, high concentrations of IL-13 were associated with an increased risk of complicated appendicitis [OR 1.02 (95% CI 1.01–1.04) p = 0.005], which remained in the multivariate analysis [aOR 1.02 (95% CI 1.01–1.04), p = 0.01]." (PMID 35586830, 2022). "This cohort study aimed to evaluate the association of serum concentrations of IgE, IL-4, IL-9, and IL-13 in children with the risk of complicated appendicitis." (PMID 35586830, 2022). "This is an interesting finding, warranting future research on the diagnostic performances of IL-13, preferably in conjunct with a clinical prediction score for pediatric appendicitis." (PMID 35586830, 2022). "In the univariate logistic regression analysis, higher concentrations of IL-13 were significantly associated with an increased risk of complicated appendicitis (OR 1.02 (95% CI 1.01–1.04), p = 0.005)." (PMID 35586830, 2022). "In contrast to our hypothesis, concentrations of the Th2-associated IL-13 were significantly elevated in the children with complicated appendicitis." (PMID 35586830, 2022). "The aim of the present study was to evaluate whether concentrations of IgE and the Th2-associated cytokines interleukin (IL)-4, IL-9 and IL-13 in serum are associated with the risk of complicated appendicitis in children." (PMID 35586830, 2022). "High levels of IL-13 seem to be associated with an increased risk of complicated appendicitis." (PMID 35586830, 2022). "In the logistic regression, high concentrations of IL-13 were associated with an increased risk of complicated appendicitis, even when adjusting for age, symptom duration and the presence of an appendicolith–a finding that might offer novel future diagnostic possibilities." (PMID 35586830, 2022). "This was echoed by a retrospective study of children with acute appendicitis, where IL-6 and other biomarkers such as CRP, immunoglobulin E (IgE), and interleukin-13 (IL-13) were found to be independent risk factors for complicated appendicitis (p < 0.05)." (PMID 38892260, 2024). "In ALF, the highest concentrations of IL-4 and IL-13 were present in complicated appendicitis, perforated appendicitis and peritonitis, which are associated with more destructive forms of appendicitis (unpublished data)." (PMID 38673802, 2024). "Children with complicated appendicitis had significantly higher concentrations of IL-9 and IL-13 compared to children with uncomplicated appendicitis." (PMID 35586830, 2022). "Serum concentrations of IL-4 and IL-9 did not affect the risk of complicated appendicitis, but at the same time high levels of IL-13 were associated with an increased risk of complicated appendicitis." (PMID 38673802, 2024). "High concentrations of serum IL-13 seem to be associated with an increased risk of complicated appendicitis in children, while serum total IgE, IL-4 and IL-9 do not seem to be associated with the risk of complicated appendicitis." (PMID 35586830, 2022). "A recent study has also shown an association of single nucleotide polymorphisms (SNPs) of IL-13 with appendicitis, but not for severe appendicitis." (PMID 35586830, 2022).
astrocytoma (3 papers, 2015 to 2023). "Il13Rα2 receptor specific for astrocytoma cells had been previously investigated as a route to specific delivery of drugs to GB cells based on different types of nanocarriers conjugated with IL13 homing-peptide being a ligand for Il13Rα2." (PMID 37508570, 2023). "In the present study, we have examined whether IL-13 can signal through IL-13Rα2 via AP-1 pathway in GBM cell lines and in astrocytoma and GBM specimens in situ." (PMID 30572904, 2018).
autoimmune thyroid disease (3 papers, 2021 to 2023). Inflammatory disease of the thyroid gland due to autoimmune responses leading to lymphocytic infiltration of the gland. "Cytotoxic T-lymphocyte associated protein 4 (CTLA-4) inhibition worsened autoimmune thyroiditis in mice via the production of interleukin (IL)-2, interferon gamma, IL-10, and IL-13 cytokines." (PMID 34234669, 2021).
bacterial meningitis (3 papers, 2017 to 2023). Inflammation of the membranes surrounding the brain and spinal cord due to a bacterial infection. "A systematic review of cytokine levels in lumbar CSF in TBM found that IFNγ, IL-13, and sIL-2R were increased in TBM compared with other causes of bacterial meningitis, whereas TNF, IL-1β, IL-1Ra, IL-8, IFNγ, sIL-2R, IL-13, and IL-17 were increased compared to viral or aseptic meningitis." (PMID 38264653, 2023). "One study showed that there was also significant elevation of cathelicidin LL-37, interleukin (IL)-13 and vascular endothelial growth factor (VEGF) and reduction of IL-17 in the CSF of children with TBM, compared to children with viral and bacterial meningitis." (PMID 32937808, 2020).
brucellosis (3 papers, 2018 to 2019). Brucellosis is a bacterial infection that spreads from animals to people via unpasteurized dairy products or by exposure to contaminated animal products or infected animals. "The aim of the present study was to investigate the relationship between TNF-α, IL-12, and IL-13 gene polymorphisms and predisposition to brucellosis." (PMID 31818255, 2019). "IL-13 (−1512A/C) was associated with Brucellosis risk in dominant model (OR (95% CI) = 2.17 (1.02–4.62)), P-value = 0.041." (PMID 31818255, 2019). "IL-13 (− 1512 A/C) was associated with brucellosis risk in dominant model (OR (95% CI) = 2.17 (1.02–4.62)), P = 0.041)." (PMID 31818255, 2019). "The aim of the present study was to investigated the association between TNF-α)- 238 G/A), IL-12 (+ 1188 A/C), and IL-13 (− 1512 A/C and − 1112 C/T) gene polymorphisms and their serum levels and susceptibility to brucellosis comparison to healthy subjects." (PMID 31818255, 2019). "Serum levels of IL-13 were (4.23 ± 13.95, 2.30 ± 1.62) pg/ml in brucellosis and controls, respectively." (PMID 31818255, 2019).
Chagas disease (3 papers, 2012 to 2026). A parasitic infection caused by Trypanosoma cruzi. "Our study is the first that clearly shows a contribution of the IL-4Rα ligand IL-13 to the susceptibility to experimental Chagas disease in vivo." (PMID 30555475, 2018). "Because this arginase inhibition resulted in a decreased susceptibility to experimental Chagas disease our study supports in summary the conclusion that IL-13/IL-4Rα-driven Arg-1 expression contributes to the permissiveness of the host to T. cruzi infection." (PMID 30555475, 2018). "The poor expression of IL-4 and IL-13 after experimental infection of wildtype mice with T. cruzi nearly exclude a reasonable analysis of the contribution of the IL-4Rα-Arg-1 pathway in susceptibility to experimental Chagas disease." (PMID 30555475, 2018). "Hence, to determine the hypothetical effect of the IL-4Ra on the outcome of Chagas disease we infected mice with T. cruzi which overexpressed IL-13 specifically in T cells." (PMID 30555475, 2018). "Taken together, IL-13 overexpression did not negatively affect the generation of NOS2-dependent effector responses in CAM, the pro-inflammatory cytokine release and inflammation during experimental Chagas disease." (PMID 30555475, 2018).
chronic GVHD (3 papers, 2015 to 2022). "However the proportion of CD4+ T cells generating cytokines, such as TNF-α, TGF-β, IL-21 and IL-13, which are critically involved in chronic GVHD, was significantly reduced in mLN from CpG-proB recipients, while only IL-13-expressing CD4+ T cells were diminished in pLN." (PMID 35479094, 2022).
Coeliac Disease (3 papers, 2013 to 2021). "Moreover, the Th2-associated cytokines IL-5, IL-10 and IL-13 were elevated in children with coeliac disease compared to controls." (PMID 25212572, 2015). "Our finding of cytokines IL-5, IL-10 and IL-13 belonging to the Th2 response being elevated significantly in coeliac disease was surprising, as a Th2 cytokine pattern has not been considered previously to be central in the immune reaction in coeliac disease." (PMID 25212572, 2015). "Serum samples were collected in 19 of 26 children with coeliac disease after starting a gluten-free diet after 1·5 ± 0·36 years [median ± standard deviation (s.d.)] and analyses performed for cytokines IFN-γ, IL-5, IL-10, IL-12p70 and IL-13." (PMID 25212572, 2015). "This speculation would be in line with a previous finding of significantly higher levels for IL-6, IL-13, IL-10, IL-1b, and TNF-α in combination with significantly lower 25(OH)D concentrations in screening-detected celiac disease cases compared with healthy controls." (PMID 34604278, 2021). "IL-13, but not IL-10, was found elevated in a study of refractory coeliac disease." (PMID 25212572, 2015).
cutaneous T-cell lymphoma (3 papers, 2023 to 2024). "The interleukins IL-4 and IL-13 are increasingly recognized contributors to the pathogenesis of cutaneous T cell lymphomas (CTCLs), and their role in disease-associated pruritus is accepted." (PMID 38398754, 2024). "The finding of a statistically significant association between Dupilumab use and progression/exacerbation of cutaneous T-cell lymphoma may sound surprising and contradict the literature, in that IL4 and IL13 are overexpressed in this malignancy and their dual suppression should inhibit the tumor." (PMID 37954855, 2023).
eczema herpeticum (3 papers, 2020 to 2022). "Moreover, clinical trials showed that treatment with the monoclonal antibody dupilumab, which inhibits IL-4/IL-13 signaling, was associated with a decreased risk of eczema herpeticum." (PMID 35969080, 2022).
eosinophilic gastroenteritis (3 papers, 2015 to 2023). "Transcriptomic analysis of gastric biopsies obtained from patients with eosinophilic gastroenteritis reveals activation of the Th2 cytokine signaling pathways IL-4, IL-5, and IL-13." (PMID 31730503, 2019). "In clinical studies increased secretion of IL-4, IL-5 and IL-13 by peripheral blood T cells has been reported in patients with eosinophilic gastroenteritis." (PMID 27840774, 2015).
epilepsy (3 papers, 2015 to 2023). A brain disorder characterized by episodes of abnormally increased neuronal discharge resulting in transient episodes of sensory or motor neurological dysfunction, or psychic dysfunction. "Epilepsy was associated with IL-5 (r = 0.347, P = 0.0020), IL-10 (r = 0.328, P = 0.0036), IL-12p70 (r = 0.370, P = 0.0001), IL-13 (r = 0.346, P = 0.0021), and F2-IsoPs (r = 0.536, P < 0.0001)." (PMID 26236424, 2015). "This suggests that VNS treatment of epilepsy may be achieved by upregulating anti-inflammatory factors such as IL-13." (PMID 37470000, 2023). "On the one hand, MSC grafts and epilepsy may result in large astrocyte scars which can physically obstruct IL-13 from reaching the hippocampus." (PMID 33013320, 2020). "Therefore, whether IL-13 has a protective effect on the pathophysiology of epilepsy is still controversial, and more powerful evidence is needed for verification." (PMID 33013320, 2020). "In this study, there was also a marked elevation in the levels of cytokines other than IL-1ra after epilepsy, including CCL3, IL-12p70, IL-13, IL-17, and bFGF." (PMID 37470000, 2023).
gastroesophageal reflux (3 papers, 2014 to 2025). "To explore this possibility, we studied the effects of simulated gastroesophageal refluxate solutions (containing acid and/or bile salts) on eotaxin-3 secretion by esophageal epithelial cells with and without IL-13 stimulation." (PMID 24988451, 2014).
Glucose intolerance (3 papers, 2021 to 2025). Glucose intolerance (GI) can be defined as dysglycemia that comprises both prediabetes and diabetes. "Eosinophil-derived IL-4 and IL-13 promote M2 macrophage polarization and adipocyte maturation, enhancing lipid storage and insulin sensitivity, whereas eosinophil deficiency leads to impaired adipogenesis, ectopic lipid deposition, and glucose intolerance." (PMID 41010970, 2025). "IL-4 and IL-13, which are both induced by type 2 immune responses, decrease inflammation in metabolic organs by inducing M2 polarization of macrophages, leading to the improvement of systemic glucose intolerance in mice." (PMID 34073755, 2021). "Our published work on Il13-KO and the current study demonstrate that mice lacking whole-body or preadipocyte IL-13/IL13Rα1 signaling show increased weight gain and glucose intolerance." (PMID 40198135, 2025).